ATF4 (activating transcription factor 4)
Diseases named in the same sentence as ATF4 in open-access papers (continued):
Sharing a sentence is not in itself a finding about the gene and the disease.
cancer (continued). "Subsequently, we revealed that CAFs secrete TGF-β1 to upregulate the expression of ATF4 in PDAC cells via the SMAD2/3 pathway and induce cancer progression, cancer stemness, and gemcitabine resistance." (PMID 33782384, 2021). "Analysis of gene expression profiles in FTS-treated cancer cells points to the upregulation of stress response genes, such as ATF3 and ATF4." (PMID 33676427, 2021). "Our results indicate that neutrophil arginase induces ER stress in cancer cells through PERK signaling, which involves activation of the PERK → eiF2α → ATF4 → CHOP axis that eventually leads to cell death." (PMID 34131176, 2021). "In the process of UPRmt, various components are activitated to enhance the mitochondria-nucleus retrograde signaling to promote carcinoma progression, including hypoxia-inducible factor (HIF), activating transcription factor ATF-4, ATF-5, CHOP, AKT, AMPK." (PMID 34717757, 2021). "Altogether, these results seem to strongly support an involvement of MPV17 in cancer cell proliferation as MPV17 silencing was consistently accompanied by a reduction of both cell proliferation rate and ATF4 protein abundance." (PMID 32155188, 2020). "On top of these genes, NRF2 also regulates the expression of genes needed to fulfill the constant demand of protein synthesis of cancer cells such as PHGDH, PSAT1, PSPH, SHMT1, and SHMT2 by activating the critical effector ATF4." (PMID 32106613, 2020). "The transcription factor ATF4 is a critical effector of the ISR and is highly expressed in many cancers as a result of extrinsic stress or direct activation by constitutive oncogene expression." (PMID 31770110, 2020). "(A) mRNA-expression of ER-stress markers ATF6, ATF4, EIF2AK3, GADD34, EDEM1, DDIT3 and HSPA5, in stellate cells (LX2) co-cultured with cancer cells (HepG2 or Huh7) and treated with 4μ8C or control." (PMID 33103995, 2020). "Tunicamycin increases ATF4 and CHOP activity via GRP78 up-regulation in various cancer types and induces autophagy and apoptosis." (PMID 32879309, 2020). "ATF4 is a critical transcriptional factor of UPR and is frequently upregulated in various human tumors and cancers." (PMID 31064130, 2019). "At the molecular level, we showed that ATF4 significantly upregulates the mRNA and protein levels of ZEB1, which is a critical transcriptional repressor of E-cadherin and promotes EMT and cancer metastasis." (PMID 31064130, 2019). "Previous studies have demonstrated that ATF4 is involved in chemoresistance via transcriptional regulation of membrane transporters and enzymes required for GSH biosynthesis in cancer cells." (PMID 31519193, 2019). "Collectively, these results indicate that kurarinone triggers ATF4 activation through PERK-eIF2α signaling and exerts cytostatic effects on cancer cells." (PMID 31461933, 2019). "Activation of ER stress has been described to help cancer cells in EMT by overcoming the stress of cell detachment and this involves both the IRE-XBP1s and PERK-eIF2α-ATF4 signaling pathways." (PMID 30813301, 2019). "Together, we herein established the RTK-initiated transcription regulatory network, which highlighted transcriptional factors ATF4 and MYC as the key nodes in preferentially reprogramming the metabolic network in cancers with aberrant EGFR or FGFR." (PMID 31221965, 2019). "Treating obese mice with celastrol, a drug known to promote apoptosis in cancer cells via activation of IRE1, ATF4, and CHOP, reduces airway hyperresponsiveness and IL-17 production." (PMID 30978945, 2019). "Eeyarestatin has been demonstrated to activate ATF3 and ATF4 and to induce the expression of the pro-apoptotic NOXA in malignant melanoma cells, indicating its anti-cancer activity." (PMID 31739582, 2019). "All three genes are induced in hypoxic conditions via PERK/ATF4 and their knockdown, or knockdown of PERK and/or ATF4, reduces cancer cell proliferation (TRIB3 and ULK1), survival (ULK1), and migration (LAMP3) in hypoxia." (PMID 30248920, 2018).
cancer (continued). "The PD1/PDL1 reverse signaling can activate the eIF2α/ATF4 pathway through IDO1 whose inhibitors are actively undergoing clinical trials in combination with anti-PD1 or anti-PDL1 antibodies to treat cancers." (PMID 30305853, 2018). "It is possible that the ATF4 regulation of KRT16 is inhibited in normal cells, but is somehow activated during cancer progression processes." (PMID 29420561, 2018). "In this context, SLC7A11 expression was also dependent on the transcription factor ATF4, which is known to cross talk with NRF2 in cancer cell metabolism." (PMID 28967864, 2017). "Induction of autophagy by ATF4 and CHOP helps several human cancer cell lines adapt to hypoxia, whereas a previous study suggests that cyclophilin B mediates the adaptation of tumor cells to hypoxia through ubiquitin-dependent degradation of CHOP." (PMID 29230213, 2017). "ATF4 also promotes multidrug resistance (MDR) expression, a major challenge to cancer treatment, through transactivation of signal transducer and activator of transcription 3 (Stat3)." (PMID 28860159, 2017). "ROS was also enhanced in carnosic acid-treated cancer cells, and NAC considerably reduced carnosic acid-induced CHOP and ATF4 expression." (PMID 26188905, 2015). "Our work also identified several cancer-related genetic signatures in the ER-Golgi network, including IKK, NFκB and ATF4." (PMID 25522186, 2014). "Lipid peroxidation and cell death in cancer cells overexpressing ATF4 did not increase throughout the entire process of ferroptosis induction." (PMID 39679775, 2025). "At the same time, ATF4/CHOP axis was responsible for apoptosis and caspase activation in cancer." (PMID 40830980, 2025). "It was recently shown that cancer cells which survive brief treatment with cytotoxic concentrations of BH3 mimetics induce MOMP and cytochrome c release, which activates the ISR including ATF4 and its target gene ATF39." (PMID 41249572, 2025). "In addition to apoptosis, activation of ATF4 and ISR by ONC201 has been shown to induce G1 phase arrest in many cancer types viz." (PMID 40305155, 2025). "Subsequent studies have sought to explain this resistance, revealing that transcription factors and kinases like activating transcription factor 4 (ATF4) and mechanistic target of rapamycin complex 1 (mTORC1) play pivotal roles in maintaining Asn homeostasis in cancer cells." (PMID 39762761, 2025). "Because ATF4-induced glutamine transporters, such as ASCT2 confer resistance to CB-839, we hypothesized that inhibiting these transporters might enhance cancer cell sensitivity to CB-839." (PMID 40223274, 2025). "ATF4 protein half-life remained unchanged in both cancer and normal cells after DT-061 or Tg exposure." (PMID 39349971, 2024). "Transcription factor (TF) motifs, including CEBPB (+), FOSB (+), SAP30 (+) and ATF4 (+), were significantly upregulated in CNV high cancer cells, while IRF3 (+), ETV7 (+), STAT1 (+) and IRF7 (+) were downregulated, indicating promising new regulatory networks driven by TFs in OS cells." (PMID 36596773, 2023). "The subnetworks of ATF4, PIK3R1, and PIK3R3 filtered out from our study have been also shown to participate in TNF signaling pathway, since these hub genes involve immune regulation in cancer and AR disease." (PMID 37430199, 2023). "We confirmed that the depletion of CHI3L1 induced the phosphorylation of PERK and increased the eIF2α and ATF4 levels in cancer cells, but not normal cells." (PMID 37215572, 2023).
cancer (continued). "These NDCs maintain chemosensitivity as parental cancer cells and gain malignant properties; in particular, these NDCs demonstrate enhanced metastatic capacities through ATF4‐dependent nonclassical NF‐κB signaling activation." (PMID 36739602, 2023). "The repopulating cancer cells acquired enhanced tumorigenic and metastatic capacities by inducing activating transcription factor 4 (ATF4)‐dependent nonclassical NF‐κB signaling activation." (PMID 36739602, 2023). "Because Sirt5 supports glutamine metabolism in cancer cells by protecting GAC from degradation, we examined whether Sirt5 expression was increased in a manner like ATF4 in response to metabolic stress." (PMID 35963851, 2022). "CREB3 induces GBM cell proliferation and invasion by inhibiting apoptosis via downregulating proapoptotic proteins—Bax, active caspase 3, p-PERK, p-eIF2α, and ATF4, suggesting that CREB3 might inhibit anti-cancer drug-induced apoptosis." (PMID 36358691, 2022). "However, a recent study reports that the induction of ER stress in cancer cells activates the PEAK/eIF2α/ATF4 signal pathway and that GADD34 induced by severe or chronic ER stress inhibits the PEAK/eIF2α/ATF4 signal pathway via the de-phosphorylation of eIF2α." (PMID 35269802, 2022). "The impact of OxA treatment on chemoresistant tumors, on the expression of various proteins such as Nrf2, p-eIF2α, ATF4, PolQ, FoxM1, and Bcl2, which are involved in cancer chemoresistance, is not shown." (PMID 35747788, 2022). "Our previous study showed that ATF4 is upregulated in NSCLC and may contribute to cancer development." (PMID 33628101, 2021). "We previously showed that cell‐nonautonomous signaling among cancer cells drives, paradoxically, a reduction of ATF4 and CHOP activation downstream of eIF2α, hence avoiding apoptosis under condition of acute stress." (PMID 34698427, 2021). "To verify our hypothesis we tested a new compound (ONC201) that was reported to induce an integrated stress response ATF4- and CHOP-dependent and in phase I and II trials in other cancer models." (PMID 33608585, 2021). "Compared to treatment with ICG001 alone, the invasion ability of cancer cells was significantly increased by treatment with ICG001 and ATF4 cDNA (p < 0.05), indicating that the invasion-promoting function of ATF4 is not mediated only by Wnt/β-catenin signaling." (PMID 33628101, 2021). "Our data show that ATF4 expression was mainly detected in nucleus in both HBE and cancer cells." (PMID 33628101, 2021). "However, compared to treatment with ICG001, the invasion ability of cancer cells treated with both ICG001 and ATF4 cDNA significantly increased (p < 0.05), which indicates that the function of ATF4 was not dependent only on Wnt/β-catenin signaling." (PMID 33628101, 2021). "The data show that, when cancer cells were treated with Wnt3a, ATF4 did not further enhance the activity of canonical Wnt signaling, which suggests that ATF4 regulates Wnt/β-catenin signaling mainly through modulating β-catenin stability, similar to Wnt3a." (PMID 33628101, 2021). "Taken together, GCN2/ATF4/REDD1 axis induced by amino acid deprivation promotes cell survival signal, which might be a potential target for cancer therapy." (PMID 34862383, 2021). "This might be due to a feedback loop between ERO1 levels and the levels of the upstream CHOP and ATF4, which are involved in the transcription of VEGF, the angiogenic switch and cancer metastases." (PMID 33531624, 2021). "Very interestingly, recent work from the Muñoz-Pinedo laboratory highlights that multiple cancer cell types produce chemokines and cytokines (such as IL6, IL-8...) in an ATF4- and NF-κB-dependent manner in response to starvation, inducing the chemotaxis of macrophages, B cells and neutrophils." (PMID 32365592, 2020).
cancer (continued). "Glucose deprivation, to which cancer cells are particularly sensitive, induces ER stress and FADD/Caspase-8-dependent apoptosis in HeLa cells through the upregulation of TRAIL-R1 and 2 downstream of ATF4 and CHOP." (PMID 32365592, 2020). "As a consequence, cancer cells certainly share higher expression of PERK and its main downstream effectors including phosphorylated eukaryotic translation initiation factor 2α (p-eIF2α), ATF4, CHOP and nuclear factor-like 2 (Nrf2)." (PMID 31491919, 2019). "Interestingly, ATF4 downstream effectors ULK1 and LAMP3 were found to be overexpressed in breast cancer and correlated with more advanced cancer stage." (PMID 31491919, 2019). "For these implications, it appears likely that ATF4 may be a regulator of metabolic and cell death adaption following modulation of LXR signaling in cancer cells." (PMID 31468706, 2019). "Moreover, the phosphorylation levels of eIF2α and the protein expression of ATF4 and xCT of the cisplatin-resistant AGS–CisR cancer cells were higher than those of the parental AGS cells." (PMID 30380689, 2018). "Knockdown of ATF4 and PUMA inhibited doxycycline-induced apoptosis for the sphere-forming culture cells, suggesting that the ER stress response is a key player for antibiotics-induced apoptosis for cancer stem-like cell and a new stratagy for cancer therapy." (PMID 29184058, 2017). "CHOP and DR5 were not enhanced in ATF3- and ATF4-depleted cancer cells treated with bortezomib, a proteasome inhibitor." (PMID 26188905, 2015). "Recent observations in cancer cell lines have shown that DHA may induce ER stress and increase ATF4 both at the protein and transcriptional levels." (PMID 24641624, 2014). "Positive immunoreactivity for ATF4 was observed primarily in the cytoplasm of carcinoma cells and non-cancerous epithelial cells." (PMID 25078779, 2014). "ATF4 is also known as CREB2, a member of CREB family, which is known as a key regulator in the control of cellular gene expression, regulating cell cycle and growth factor genes of which aberrant expression is observed in certain cancers." (PMID 19057705, 2008). "In addition, blocking ATF4 induction can reduce the cellular response to stressors, as seen with the use of siRNA to inhibit ATF4, which decreased the response to stress-inducing agents like NXP800 in cancer cells." (PMID 40608151, 2025). "Therefore, because of the crucial role of ATF4 under glutamine stress conditions, the modulation of ATF4 and ASCT2 may offer a promising therapeutic target for cancer treatment." (PMID 40223274, 2025). "The lncRNA FERRIN, which is produced under conditions of glutamine starvation induced by the transcription factor ATF4, interacts with the RNA-binding protein hnRNPK, thereby promoting its binding to and stabilizing SLC7A11, and consequently promoting the proliferation of cancer cells." (PMID 40598593, 2025). "Furthermore, impairing host use of folate for 1C-metabolism processes via MTX, a drug that is widely used in anti-cancer therapies, led to increased growth in WT cells but not ATF4 KO cells." (PMID 40811546, 2025). "Moreover, our results show that DT-061 modulation of PP2A regulates TFE3 to promote ATF4 expression and activity in both cancer and non-malignant cells, albeit distinctive downstream response mechanisms are activated, resulting in two distinct outcomes." (PMID 39349971, 2024). "In addition, pretreatment of cancer cells with a PERK inhibitor augmented TG-induced apoptosis, particularly in CCDC85AKO cells, accompanied by JNK activation and attenuation of eIF2〈 phosphorylation and ATF4 expression (right)." (PMID 37534255, 2023).
cancer (continued). "In cancer cells, ACF has been shown to inhibit the unfolded protein response (UPR) pathway via inhibition of eukaryotic translation initiation factor 2A (eiF2a) phosphorylation and downregulation of the activating transcription factor 4 (ATF4) transcriptional program." (PMID 36227697, 2022). "In addition to the canonical regulation of ATF4 translation by the ISR pathway, we find that mTORC2 activation increases ATF4 transcription which is critical for sustaining ATF4 pools during pro-longed exposure of cancer cells to stress." (PMID 35963851, 2022). "Since the apatinib treatment and ATF4 knockdown led to the cutoff of glutamine metabolism, we speculated that cancer cells might have difficulty surviving in the absence of nutrition." (PMID 35864117, 2022). "Because previous literature suggests that extracellular matrix detachment increases oxidative stress in cancer cells, hypoxia-mediated induction of NRF2 and Atf4 may play a critical role in priming metastatic cells to survive in high stress conditions, including during matrix detachment." (PMID 35847893, 2022). "However, further studies indicate that there may be different molecular functions of ATF4 in HBE and cancer cells." (PMID 33628101, 2021). "However, we found differences in the response of the various cancer cell types to different ferroptosis inducers, and our and the published results together suggest that the roles of YAP/TAZ and ATF4 in ferroptosis regulation appear to be cell context‐dependent." (PMID 34664408, 2021). "Likewise, EGFR inhibitor Gefitinib could affect both ATF4 and MYC expression in EGFR mutant cancer cells and xenograft models." (PMID 31221965, 2019). "Furthermore, EMT gene expression signature has been correlated with ECM protein secretion and ATF4 expression (but not XBP1) in various cancers including breast and colon." (PMID 31064137, 2019). "When we examined the underlying mechanism by which Ler overcomes the resistance of cancer cells to Btz, we found that Ler co-treatment markedly enhanced Btz-induced increases in poly-ubiquitinated protein accumulation, PERK and eIF2α phosphorylation, and ATF4 and CHOP levels." (PMID 31817163, 2019). "Our results indicate that although KRT16 gene contains a functional ATF4-responsive DNA element, its regulation by ATF4 is conditional, and in particular, the gene responds to ATF4 in the two patient-derived cancer cell lines, but not in the cell lines transformed in vitro." (PMID 29420561, 2018). "Furthermore, despite the fact that ATF4 itself was not deregulated by Ocoxin in all the analyzed cancer models, it arises as a central protein in the correlation among the genes altered by the compound (except for KIF20A, RAD54L and ESPL1) in common in COAD, PAAD, PRAD and TNBC." (PMID 40176904, 2025). "Indeed, ATF4-knockout cells showed dramatically reduced levels of ASNS protein (Fig. EV7A,B), indicating a role for ATF4 not only in stress-induced expression, but also in the basal expression of this enzyme, in agreement with previous observations in cancer cell lines." (PMID 40691417, 2025). "In drug-resistant NSCLC, apatinib inhibited GLS1, forcing cancer cells to initiate the amino acid response (AAR), which induced SLC1A5 expression through the transcription factor ATF4 to compensate for extracellular glutamine acquisition, and silencing ATF4 could relieve resistance." (PMID 39061847, 2024). "Moreover, our data also showed that the function of ATF4 to regulate cancer cell invasion was not dependent on Wnt/β-catenin signaling, and there may be other molecular mechanisms involved." (PMID 33628101, 2021). "Under our experimental conditions, we observed that treatment of cancer cell lines with VAE resulted in phosphorylation of EIF2α, but not in increased expression of ATF4 or CHOP." (PMID 40369535, 2025).